ENSG00000285269 (novel transcript, SLC35D2-HSD17B3 readthrough)
Synonyms: SLC35D2-HSD17B3
Gene: Protein-coding gene on chromosome 9 (96,235,331 to 96,352,058, reverse strand). Ensembl gene ENSG00000285269.
Genetic constraint (gnomAD): Missense variants: 51 observed, 57.43 expected, observed/expected ratio (o/e) 0.89, 90% interval 0.71 to 1.12. Synonymous variants: 26 observed, 24.63 expected, observed/expected ratio (o/e) 1.06, 90% interval 0.77 to 1.46.